RPL37P1 (ribosomal protein L37 pseudogene 1)
Synonyms: bA563A22B.2; RPL37_9_1698
Gene: Processed pseudogene on chromosome 20 (35,588,324 to 35,588,607, forward strand). Ensembl gene ENSG00000227401.
Diseases named in the same sentence as RPL37P1 in open-access papers:
RPL37P1 is named in the same sentence as 1 disease in open-access papers, as found by Europe PMC text mining. Sharing a sentence is not in itself a finding about the gene and the disease. The quoted sentences say what the papers report.
cancer (1 paper, 2025). A tumor composed of atypical neoplastic, often pleomorphic cells that invade other tissues. "In summary, FAT4 and RPL37P1 play important roles in reprogramming the TME and have the potential to become a cancer prognostic marker and therapeutic target for C1 subtype." (PMID 41019085, 2025).